MOG (myelin oligodendrocyte glycoprotein)
Diseases named in the same sentence as MOG in open-access papers (continued):
Sharing a sentence is not in itself a finding about the gene and the disease.
optic neuritis (continued). "In adults, MOG antibody is predominantly seen in association with NMO/NMOSD, including bilateral and/or recurrent optic neuritis, and transverse myelitis, but rarely seen in patients with MS." (PMID 26919719, 2016). "Myelin oligodendrocyte glycoprotein antibodies (MOG-IgG) are present in a subset of aquaporin-4 (AQP4)-IgG-negative patients with optic neuritis (ON) and/or myelitis." (PMID 27802825, 2016). "In the present study, we systematically evaluated the clinical and paraclinical features of a large cohort of 50 almost exclusively Caucasian patients with MOG-IgG-positive optic neuritis (ON) and/or LETM." (PMID 27793206, 2016). "Using cell-based assays, serum MOG antibody has been shown to be primarily associated with pediatric acute disseminated encephalomyelitis (ADEM), optic neuritis (ON), transverse myelitis (TM), and aquaporin 4 antibody-negative neuromyelitis optica (NMO)." (PMID 26919719, 2016). "Antibodies against myelin oligodendrocyte glycoprotein (MOG-IgG) have been detected in some patients with AQP4-IgG seronegative NMO as well as with recurrent optic neuritis, longitudinally extensive transverse myelitis, MS and SLE." (PMID 26950113, 2016). "In the meantime, several studies by us and others have confirmed the association of MOG-IgG with NMO and with related disorders such as isolated optic neuritis (ON) or myelitis." (PMID 27788675, 2016). "The objective of this study was to describe optic neuritis (ON)-induced neuro-axonal damage in the retina of MOG-IgG-positive patients in comparison with AQP4-IgG-positive NMOSD patients." (PMID 27802824, 2016). "In BN MOG-EAE 90% of immunized animals display severe optic neuritis with apoptotic cell death of retinal ganglion cells (RGCs)." (PMID 26426258, 2015). "As MOG-induced optic neuritis and ONT both affect RGC axons, these different model systems are most suitable for a direct comparison of neurodegenerative mechanisms under autoimmune inflammatory and non-inflammatory conditions." (PMID 26426258, 2015). "High anti-MOG antibody titers are frequently observed among pediatric patients with recurrent optic neuritis." (PMID 25434485, 2014). "In conclusion, our results provide evidence that astrocytes play a key role in the development of optic neuritis secondary to MOG-induced EAE." (PMID 22963651, 2012). "MOG-antibodies, which target the central nervous system-specific MOG protein, have been associated with age-dependent disease phenotypes, including ADEM in younger children and optic neuritis or myelitis in older individuals." (PMID 40388729, 2025). "Relapsing optic neuritis occurs in 30-50% of patients with MOG-IgG." (PMID 40547008, 2025). "Similarly, in humans, optic neuritis has been described as a rare sequela of COVID-19 but appears to be more related to antibodies against myelin oligodendrocyte glycoprotein and aquaporin-4." (PMID 40733579, 2025). "The involvement of MOG-IgG in non-optic neuritis ocular inflammation suggests that MOG or similar antigens may be present or expressed in other ocular tissues, or that the immune response has systemic manifestations." (PMID 41153632, 2025). "The presence of autoantibodies against myelin oligodendrocyte glycoprotein (MOG) is a hallmark of MOG antibody-associated disease (MOGAD), a recently defined demyelinating disease entity presenting with core clinical features of optic neuritis, myelitis, and acute disseminated encephalomyelitis." (PMID 40757033, 2025). "Anti-MOG antibodies were positive (titer of 1:1000), while anti-AQP4 antibodies were negative, rapidly confirming a serological diagnosis of anti-MOG antibody-associated optic neuritis and perineuritis." (PMID 41393590, 2025). "Given that up to 50% of children presenting with demyelination under the age of 10 years will have MOGAD as a final diagnosis, all children in this age group with a first presentation consistent with demyelination, including optic neuritis, should be tested for MOG IgG." (PMID 38783085, 2024).
optic neuritis (continued). "Identifying AQP4-Ab (aquaporin 4-antigen) and MOG-Ab (oligodendrocyte glycoprotein antibodies) is pivotal for individuals having optic neuritis undergoing various therapies, as these may lead to different prognoses." (PMID 38672703, 2024). "Anti-MOG optic neuritis is comparatively severe, with visual acuity worse than 20/200." (PMID 39598329, 2024). "Thus, the purpose of this study was to determine the longitudinal changes in the pVEPs and the thickness of the pRNFL in a young Japanese girl who experienced acute optic neuritis and tested positive for anti-MOG antibodies." (PMID 39184699, 2024). "The severe prolongation of the implicit times in our case may be due to a blocking of neurotransmission by the anti-MOG antibodies seropositive optic neuritis." (PMID 39184699, 2024). "In addition, there are no reports on the longitudinal changes of the pVEPs and thicknesses of the optic nerve during the course of pediatric anti-MOG antibodies seropositive optic neuritis." (PMID 39184699, 2024). "We aim to report this case of isolated optic neuritis with a positive anti-myelin oligodendrocyte glycoprotein antibody to highlight the prognosis of myelin oligodendrocyte glycoprotein disease with isolated optic neuritis and how early diagnosis and treatment can affect the visual outcome." (PMID 38947608, 2024). "The autoimmune optic neuritis includes forms caused by AQP4 autoimmunity and anti-MOG-associated disease, characterized by bilateral optic neuritis, unlike MS." (PMID 38673027, 2024). "Importantly, new and more efficient treatments have become available, both for multiple slcerosis‐ related optic neuritis and MOG‐ and AQ4‐related optic neuritis." (PMID 39511714, 2024). "Optic neuritis with positivity to antibodies, such as anti-MOG antibodies and anti-aquaporin-4 antibodies, may have a poor visual prognosis." (PMID 38179351, 2023). "They proposed a new classification of autoimmune optic neuritis, including MS-associated optic neuritis (MS-ON), AQP4 antibody–associated optic neuritis (AQP4-ON), MOG antibody–associated optic neuritis (MOG-ON), and CRMP5 antibody–associated optic neuritis (CRMP5-ON)." (PMID 37448746, 2023). "This study reveals different immunological mechanisms between AQP4-ON and MOG-ON based on transcriptomics analysis of patients’ whole blood, which may expand the current knowledge regarding optic neuritis." (PMID 36969199, 2023). "Initial cerebrospinal fluid analysis was negative for all antibodies (Abs) associated with optic neuritis and other acute demyelinating syndromes, including anti-myelin oligodendrocyte glycoprotein Ab (anti-MOG-Ab)." (PMID 37565176, 2023). "The prompt administration of intravenous methylprednisolone (IVMP) has been found to improve the chances of favorable visual acuity in both NMOSD- and MOG-related optic neuritis patients, and baseline visual status has been identified as a factor that can affect visual outcomes after treatment." (PMID 36977296, 2023). "The immune attack in MOG antibody disease (MOGAD) is associated with myelin and oligodendrocyte damage, resulting in heterogeneous clinical manifestations such as optic neuritis (ON), reduced/loss of vision, myelitis, seizures, brainstem syndromes, and encephalitis." (PMID 36793713, 2023). "Therefore, compared to MOG-IgG-associated myelitis, GFAP-IgG-associated myelitis appears to have a later age of onset, is relatively rare in patients with optic neuritis, and is relatively common in those with impaired consciousness." (PMID 38020648, 2023). "MOG-IgG+ optic neuritis patients had 37% and 67% preceding infection in two series (3/8 and 6/9)." (PMID 36925938, 2023). "The diagnosis of anti-MOG brainstem encephalitis and optic neuritis was set." (PMID 36548183, 2022). "Moreover, patients with MOG-IgG–positive optic neuritis experience more frequent recurrences with shorter durations between attacks than MOG-IgG–negative optic neuritis." (PMID 35566760, 2022).
optic neuritis (continued). "Our results demonstrated that plasma LCN2 levels were significantly higher in patients with MOG-IgG–positive optic neuritis than in controls and patients with MOG-IgG–negative optic neuritis, and plasma LCN2 levels were positively correlated with MOG-IgG titers." (PMID 35566760, 2022). "Additionally, we present a review of the current literature regarding the manifestation of anti-MOG positive optic neuritis as well as anti-MOG positive encephalitis after COVID-19 infection." (PMID 36548183, 2022). "Additionally, plasma LCN2 levels were positively correlated with MOG-IgG titers in patients with optic neuritis." (PMID 35566760, 2022). "Furthermore, some reported cases of simultaneous IgG positivity had a medical history of previous optic neuritis and were tested for MOG IgG for the first time at the onset of NMDAR encephalitis." (PMID 36384491, 2022). "Our results imply that measurement of plasma LCN2 levels may be helpful in differentiating MOG-IgG–positive optic neuritis from MOG-IgG–negative optic neuritis." (PMID 35566760, 2022). "Plasma LCN2 levels may aid differentiation of MOG-IgG–positive optic neuritis from MOG-IgG–negative optic neuritis." (PMID 35566760, 2022). "However, when MOG-IgG coexisted with glial antibodies (cases 6 to 10), demyelination was dominant, such as optic neuritis, myelitis, and brainstem encephalitis." (PMID 36009058, 2022). "We found 11 eyes of six MOG antibody seropositive patients with confirmed optic neuritis and OCT images of good quality which could be used for the MOG group." (PMID 32785840, 2021). "A small case series of three patients with MOG-ON reported preferential thinning of pRNFL of some quadrants, which is in contrast to the thinning of the temporal pRNFL quadrant typically seen in MS optic neuritis." (PMID 32785840, 2021). "The diagnosis of NMOSD should not be limited to seronegative or positive AQP4 antibody in a patient presenting with optic neuritis and could still be anti-MOG optic neuritis." (PMID 34484845, 2021). "An additional important limitation is testing bias in the diagnosis of MOG-ON; as this entity is only recently described, testing for MOG-IgG antibodies may have predominantly been performed only in severe or bilateral cases of optic neuritis." (PMID 32785840, 2021). "Additionally, the onset phenotype was characteristic: 55% with optic neuritis, 21% transverse myelitis (including 7 patients with radiologically confirmed lesions in the conus medullaris, a feature frequently identified in MOG antibody mediated myelitis)." (PMID 33510701, 2020). "A Korea study showed that compare to the optic neuritis with MOG-Ab, ocular pain with ocular movement and optic disc swelling were more common in patients with optic nerve sheath enhancement (ONSE), who also exhibited a poorer initial visual acuity than did those without ONSE." (PMID 33584521, 2020). "For example, a patient with anti-NMDAR antibodies and anti-MOG antibodies will suffer from an aggressive mood disorder frequently seen in anti-NMDAR encephalitis, followed by optic neuritis and cerebral cortex lesions revealed by brain MRI, a clinical feature of anti-MOG antibody-related disease." (PMID 32668637, 2020). "Although the relationship of anti‐MOG antibodies to adult MS has not been so clear, recent studies have reported that they are strongly associated with bilateral optic neuritis in adults." (PMID 30578556, 2019). "Optic neuritis in anti-MOG syndrome exhibits some peculiar features that may distinguish it from optic neuritis in AQP4-IgG NMOSD and MS." (PMID 31212763, 2019). "Also during the further course of the disease, optic neuritis seems to be more frequent in MOG-EM than in NMOSD with myelitis being less common." (PMID 30405519, 2018). "Characteristics of MOG-IgG-associated diseases include optic neuritis as a major symptom, good response to steroid, absence of serum AQP4-Ab, and steroid-dependent relapse or disease exacerbation." (PMID 30382857, 2018).
optic neuritis (continued). "Although acute disseminated encephalomyelitis (ADEM), optic neuritis (ON) and transverse myelitis (TM) are all phenotypes known to be related to MOG antibody (MOG-Ab) seropositivity, it is clear that further clinical characterisation and understanding of treatment outcomes is needed." (PMID 29992350, 2018). "Variable response to PLEX was observed, perhaps due to timing of the procedure, MOG antibody titers, number of sessions, intensity of the relapse, the extension and site of the demyelinating event, and optic neuritis vs. transverse myelitis vs. other locations." (PMID 29064441, 2017). "While retrobulbar optic neuritis was highly common among our MOG-IgG-positive patients, lesions affecting other parts of the optic pathway should be taken into consideration as well in MOG-IgG-positive patients presenting with visual symptoms." (PMID 27793206, 2016). "MOG-IgG have further been reported in children with acute and relapsing-remitting inflammatory demyelinating encephalomyelitis as well as in a proportion of adults with inflammatory demyelinating diseases such as optic neuritis (ON)." (PMID 27802824, 2016). "Furthermore, several diagnostic studies including cerebrospinal fluid assays for MOG and aquaporin‐4 antibodies were not available in our setting, which means that antibody‐associated optic neuritis and related inflammatory disorders cannot be fully excluded." (PMID 41415515, 2025). "The growing awareness of MOGAD in recent years has elevated MOG antibody testing to a critical diagnostic tool, essential for differentiating between MS, NMO, and MOGAD, particularly in patients presenting with abnormal neurology and radiology including optic neuritis and myelitis." (PMID 38790547, 2024). "However, extensive deep retinal haemorrhages have not been described in the context of MOG-associated optic neuritis." (PMID 39569189, 2024). "Furthermore, both MvD+ and MvD- groups were comprised of comparable proportions of MS, anti-AQP4 antibody and anti-MOG antibody-positive optic neuritis as well as recurrences, and we believe that if the difference in etiology had any effect, they would have canceled out and resulted in minimal bias." (PMID 37104301, 2023). "Finally, an autoimmune mechanism may also be at play in patients with COVID-19 optic neuritis due to anti-MOG antibodies (myelin oligodendrocyte glycoprotein)." (PMID 37064029, 2023). "The results may be different in optic neuritis with positive serum aquaporin−4 or MOG antibodies." (PMID 35052875, 2022). "Therefore, close monitoring for signs of recurrence and long-term prophylactic immunosuppression may be necessary in patients with MOG-IgG–positive optic neuritis." (PMID 35566760, 2022). "The clinical phenotype of MOG-associated disorder is age-dependent: young children mostly present with acute disseminated encephalomyelitis (ADEM), whereas older children and adults manifest with optic neuritis or, less frequently, with extensive myelitis or encephalitis." (PMID 34997443, 2022). "Immunoglobulin G antibodies to myelin oligodendrocyte glycoprotein (MOG-IgG) associated disease is a rare, demyelinated disease in the central nerve system (CNS) predominately involving optic nerve, spinal cord, and brain leading to optic neuritis (ON), transverse myelitis (TM), encephalitis." (PMID 36530610, 2022). "In patients with myelin oligodendrocyte glycoprotein (MOG) antibody-associated demyelination (MOGAD), studies have shown that adults patients with MOGAD showed less frequent encephalitis (ADEM phenotype) while more frequent myelitis and optic neuritis compared to pediatric patients with MOGAD." (PMID 36569880, 2022). "Therefore, we hypothesized that measuring the plasma LCN2 levels in patients with optic neuritis may help in the diagnosis of MOG-IgG–positive optic neuritis." (PMID 35566760, 2022).
optic neuritis (continued). "Importantly, the presentation of bilateral simultaneous optic neuritis or optic neuritis with transverse myelitis is common in MOG-NMOSD and greater than that seen for AQP4-NMOSD, which invites a careful search of the diagnostic criteria, as previously reported." (PMID 29064441, 2017). "Considering the clinical presentation of optic neuritis and longitudinally extensive myelitis, we considered a diagnosis of NMO or myelin oligodendrocyte glycoprotein (MOG) antibody disease (MOGAD)." (PMID 40171223, 2025). "Transverse myelitis is another common presentation in patients with MOG-IgG, which can occur alone, alongside ADEM or optic neuritis." (PMID 40547008, 2025). "Anti-Myelin oligodendrocyte glycoprotein (MOG) and anti-metabotropic glutamate receptor 5 (mGluR5) double antibody positive encephalitis characterized by optic neuritis is extremely rare." (PMID 39151524, 2024). "In addition, two case studies reported on paediatric patients who exhibited retinal haemorrhage in the context of acute disseminated encephalomyelitis associated with optic neuritis, but in those cases, MOG antibodies were negative and unknown." (PMID 39569189, 2024). "Whilst longitudinally extensive optic neuritis is also observed in AQP4-ON, in the range of 50–79%, longer segments are more frequently involved in MOG-ON." (PMID 38783085, 2024). "This clinical picture is labeled as atypical optic neuritis and should prompt serum testing for AQP4 and MOG antibodies." (PMID 37958968, 2023). "In this paper, we report three cases of ADEM, transverse myelitis and bilateral optic neuritis in people with HIV, all of whom had MOG antibodies." (PMID 37845760, 2023). "Myelin Oligodendrocyte Glycoprotein Antibody Disease (MOGAD) is a spectrum of diseases, including optic neuritis, transverse myelitis, acute disseminated encephalomyelitis, and cerebral cortical encephalitis." (PMID 36925938, 2023). "Fourth, the study population included optic neuritis of mixed etiology, such as MS, NMOSD with anti-AQP4 antibody or MOGAD with anti-MOG antibody." (PMID 37104301, 2023). "Some typical indicators of EAE development (optic neuritis and other clinical or histological evidence) appear in C57BL/6 mice only 1–2 years after the spontaneous or MOG-accelerated evolution of EAE." (PMID 36770997, 2023). "The presence of MOG antibodies in patients with VZV infection is rare and bilateral optic neuritis from VZV is uncommon." (PMID 37845760, 2023). "The plasma LCN2 levels were positively correlated with MOG-IgG titers in patients with optic neuritis (r = 0.553, p = 0.0141); i.e., patients with higher plasma LCN2 levels demonstrated higher titer of MOG-IgG." (PMID 35566760, 2022). "In those cases, the MOG-AD manifested as ADEM and optic neuritis with meningoganglionitis, respectively." (PMID 35399911, 2022). "The antibody to MOG is involved in various demyelinating disorders of CNS, including acute disseminated encephalomyelitis (ADEM), optic neuritis (ON), myelitis, and neuromyelitis optic spectrum disorder (NMOSD)." (PMID 36532000, 2022). "Patients with MOG-IgG–positive optic neuritis had significantly higher mean plasma LCN2 levels than controls and patients with MOG-IgG–negative optic neuritis (p = 0.037)." (PMID 35566760, 2022). "Plasma LCN2 levels were positively correlated with MOG-IgG titers in patients with optic neuritis (r = 0.553, p = 0.0141); that is, patients with high plasma LCN2 levels demonstrated high MOG-IgG titers." (PMID 35566760, 2022). "The NMO-SD are defined, apart from optic neuritis and myelitis, by antibodies against aquaporin 4 (AQP4) and myelin oligodendrocyte glycoprotein (MOG)." (PMID 34226958, 2022). "We present the case of a 65-year-old patient, admitted to our clinic with optical neuritis, followed up approximately 10 days later by cervical myelitis, who tested positive for both anti-AQP4 and anti-MOG antibodies." (PMID 36341113, 2022).